E2F1 (E2F transcription factor 1)
Diseases named in the same sentence as E2F1 in open-access papers (continued):
Sharing a sentence is not in itself a finding about the gene and the disease.
bladder cancer (continued). "E2F1 is overexpressed in solid cancers, including non-small cell lung carcinoma, ovarian, prostate, and bladder cancers, colon cancer, and other digestive system malignances, and is associated with worse patient prognosis." (PMID 25136922, 2014). "Furthermore, the study suggests that SLC16A1-AS1, through its interaction with E2F1, contributes to the progression of bladder cancer." (PMID 38555465, 2024). "It has been found that SLC16A1 and SLC16A1-AS1 may together form a “head-to-head” complex unit with E2F1 promoter in muscle-infiltrating bladder cancer cells." (PMID 34631536, 2021). "To study the role of this transcription factor in bladder cancer progression, we utilized a human tissue culture model consisting of various cell lines that differ in their invasive potential according to the endogenous E2F1 expression status." (PMID 32863950, 2020). "We further demonstrate that the effect of SLC16A1/MCT1 in bladder cancer is E2F1-dependent." (PMID 32863950, 2020). "Therefore, RAD54L, a DNA repair gene in addition to E2F1, can be used as a biomarker for bladder cancer prognosis." (PMID 33261027, 2020). "Our previous study has identified E2F1 as a key gene in bladder cancer progression." (PMID 33261027, 2020). "In light of these findings, our data strongly suggest that, via supporting the acquisition of a hybrid glycolysis/OXPHOS phenotype, E2F1-triggered activation of the SLC16A1/SLC16A1-AS1 gene pair promotes bladder cancer progression by mediating metabolic plasticity." (PMID 32863950, 2020). "Our results suggest that, E2F1 and RAD54L could be used as diagnostic markers for bladder cancer progression and represent potential therapeutic targets." (PMID 33261027, 2020). "In particular, it is unclear whether there is a correlation between RAD54L and E2F1 in bladder cancer cells." (PMID 33261027, 2020). "In addition, FOXD2-AS1 can form a positive feedback loop with AKT and E2F1 to affect the malignant phenotype of bladder cancer." (PMID 33140822, 2020). "Our previous study has shown that E2F1 gene is involved in bladder cancer progression." (PMID 33261027, 2020). "Therefore, gene expression profiling data of 165 bladder cancer patients (GSE13507) were used to identify genes highly correlated with the expression of transcription factor E2F1." (PMID 33261027, 2020). "According to these findings, when exposed to a higher dose of cisplatin (10 μg/ml), bladder cancer cell lines with high TACC3 or E2F1 expression were both characterized by a strong transactivation response by Bik and Bim, which paralleled a severe downregulation of the Bcl-2 gene." (PMID 29358577, 2018). "Interestingly, an E2F1-dependent increase in transcription was found in U1 bladder cancer cells emerging from quiescence upon serum stimulation." (PMID 18267009, 2008). "Thus, the expression levels of E2F1 in five human bladder cancer cell lines were analyzed." (PMID 33261027, 2020). "Thus, the pharmacological suppression of the ‘out-of-context’ activity of this miRNA may hold promise for efficacy against E2F1-positive invasive bladder cancer and raises new hope in the miRNA therapeutics field." (PMID 31287003, 2019). "This interaction leads to deubiquitination of E2F1 and its stabilization facilitating the role of TMPO-AS1 in induction of malignant phenotypes in bladder cancer." (PMID 36467407, 2022). "As they are regulated by transcription factors E2F1 and E2F3, these two genes are also down-regulated in bladder cancer." (PMID 33855049, 2021). "FOXD2-AS1 (FOXD2 adjacent opposite strand RNA 1) is an oncogenic lncRNA that is overexpressed in bladder cancer and promoted progression and recurrence via forming a positive feedback loop with AKT and E2F transcription factor 1 (E2F1)." (PMID 32760219, 2020). "Taken together, these results demonstrate that the expression of E2F1 and RAD54L is significantly correlated with the progression of bladder cancer, and strongly correlated with its recurrence." (PMID 33261027, 2020).
bladder cancer (continued). "Tissue microarrays (TMAs) were used to determine the role of high expression levels of E2F1 and RAD54L in cancer progression and poor prognosis of bladder cancer patients." (PMID 33261027, 2020). "We unveil the mechanism of the E2F1-dependent impairment of c-NHEJ machinery and show its impact on DSB repair and bladder cancer progression." (PMID 31287003, 2019). "We also found that E2F transcription factor 1 (E2F1) and E2F transcription factor 2 (E2F2) are candidate downstream modulators regulated by KDM5B in bladder cancer and NSCLC." (PMID 30344945, 2018). "In our further study, we discovered that FOXD2-AS1 formed a positive feedback loop with Akt and E2F1, which served as a newly identified reason for consistently activated TRIB3/Akt pathway in bladder cancer." (PMID 29445134, 2018). "Five genes in this network (E2F1, E2F3, EGFR, RAF1, and RB1) significantly overlapped genes in the bladder cancer pathway from the Kyoto Encyclopedia of Genes and Genomes (KEGG) database (FDR q<0.01)." (PMID 29140994, 2017). "Our simulation results suggest that when E2F1, TGFBR1, and FGFR1 are simultaneously active, bladder cancer cells become highly invasive (EMT = 3)." (PMID 28775339, 2017). "One mechanism of how E2F1 can enhance glycolysis is the suppression of the protein deacetylase enzyme SIRT6 in prostate- and bladder cancer cells." (PMID 27631473, 2016). "Consistent with the down-regulation of SIRT6 by E2F1, The expression of SRIT6 was significantly diminished when bladder cancers invaded deeper, i.e. progressed further on the tumor staging." (PMID 25816777, 2015). "By binding to E2F1 and Sp1, respectively, BIR2 and BIR3 domains initiate E2F1/Sp1-positive-feedback-loop-dependent transcription of miR-203, inhibiting Src protein translation, which leads to further MMP2-cleaved activation and BC (Bladder Cancer) invasion." (PMID 33138314, 2020). "Next, cycloheximide was added to FOXD2-AS1 overexpressed bladder cancer cells or negative control cells to assess the half-time of E2F1." (PMID 29445134, 2018). "One recent study demonstrated that metformin could arrest bladder cancer cells in the G0/G1 phase with concomitant decreases in the expression of cyclin D1, CDK4 and E2F1, which is verified again in our study." (PMID 26245871, 2015). "Our results also demonstrated that metformin could arrest bladder cancer cells in the G0/G1 phases with concomitant decreases in the expression of cyclin D1, CDK4 and E2F1." (PMID 24351837, 2013). "Finally, wild type FOXD2-AS1 promoter was cloned into the pGL3 vector and subsequently co-transfected with E2F1 siRNAs and negative control siRNA into bladder cancer cells." (PMID 29445134, 2018). "Thus, we hypothesized that E2F1 may participate in the TACC3-mediated deregulation of the cell cycle and disease progression and may be responsible for the aggressive characteristics of bladder cancer." (PMID 29358577, 2018). "For example, we found that an L-FFL motif constituted by SNHG12, E2F1, and miR-16, and an M-FFL motif constituted by E2F1, miR-16 and AURKB could form a complex regulation motif by sharing common TF E2F1 and miRNA miR-16, which were highly dysregulated in breast and bladder cancers." (PMID 27322142, 2016). "Other cancer-related genes at 20q include E2F1, which is specifically targeted by hrHPV-mediated degradation of pRb, PIGU, which may play a role in cell cycle control and was identified as an oncogene in bladder cancer, and DNMT3B, a de novo DNA methyl transferase." (PMID 19486517, 2009). "Immunohistochemical (IHC) evaluation was used to determine protein expression levels of E2F1 and RAD54L in 17 patients with recurrent bladder cancer and 11 patients with non-recurrent bladder cancer." (PMID 33261027, 2020).
colon carcinoma (62 papers, 2003 to 2025). "Increased evidences have determined that aberrant activation of E2F1 is closely associated with a poor clinical outcome in various human cancers, and it was shown that E2F1 played a positive role in colon cancer metastasis and drug resistance." (PMID 35440604, 2022). "For example, expression of E2F1 in colon cancer was increased fourfold after the somatic mutation of miR136‐5p compared with normal tissue." (PMID 32865336, 2020). "In another study, chlorophyllin treatment has been reported to cause cell cycle arrest in HCT116 colon cancer cells through the increased expression of E2F1 and E2F4 transcription factors inhibiting the G1/S checkpoint step, which is an important cell cycle checkpoint." (PMID 40014124, 2025). "For instance, E2F1 has been shown to enhance the expression of c-Myc and p14ARF, leading to apoptosis in colon cancer cells." (PMID 39440054, 2024). "qPCR showed that LPS increased CXCL1, ELK1, ICAM1 and ZFAND5 mRNA levels, but decreased BCL2L1 and E2F1 mRNA levels in the colon cancer cells." (PMID 37705049, 2023). "LPS also increased COX2, CXCL1, ELK1, ICAM1, TNFSF10 and ZFAND5 but decreased BCL2L1, CYP19A1 and E2F1 mRNA levels in the colon cancer cells." (PMID 37705049, 2023). "In colon cancer cell models, knockdown of E2F1 was correlated with loss of RAD51 expression and RAD51-dependent DSB repair; furthermore, E2F1 and BRIT1 (MCPH1) were shown to form a complex that activates the transcription of BRCA1, CHK1, p73 and CASP7." (PMID 34208195, 2021). "As the downregulation of E2F1 was associated with a decreased expression of enzymes involved in thymidylate synthase, they suggest that these observations might explain the synergistic effect of oxaliplatin and 5-fluorouracil (5-FU) in the treatment of advanced colon carcinoma." (PMID 32967255, 2020). "In this study, we found that interfering Foxp1 by siRNA reduced the expression of E2F1 and Rb, and promoted the expression of AR and β-catenin, suggesting that Foxp1 is a tumor suppressor gene in colon cancer." (PMID 32951006, 2020). "CDK8 is known to phosphorylate E2F1 and to repress its transcriptional activity and this results in upregulated β–catenin protein in colon cancer cells." (PMID 33291686, 2020). "Our study implied that E2F3, E2F4, E2F7 and E2F8 are potential targets of precision therapy for patients with colon cancer while E2F1, E2F2, E3F3, E2F5, E2F7 and E2F8 are potential biomarkers for the diagnosis of colon cancer." (PMID 32117628, 2020). "In one study, the author noticed the low expression of decreased self-renewal ability in the colon cancer-initiating cells (CICs) through reregulated β-catenin expression via E2F1 and miR-4496 overexpression, which correlated with better prognosis." (PMID 33375517, 2020). "Kiyonari and colleagues also detected a downregulation of E2F1 after the treatment of colon cancer cell lines HCT116 and LoVo with oxaliplatin." (PMID 32967255, 2020). "In this study, the transcriptional levels of E2F1-8 in patients with colon cancer from GEPIA was examined." (PMID 32117628, 2020). "ICAT has been identified as a direct transcriptional target of E2F1, through which E2F1 interacts with Wnt/β-catenin and regulates proliferation in colon cancers." (PMID 32326181, 2020). "Following the treatment of colon cancer cells with agents that induce DNA breaks, E2F1 and γH2AX foci partially colocalized." (PMID 31534120, 2019).
colon carcinoma (continued). "We therefore decided to study the expression of FOXM1, TYMS, and E2F1 in colon cancer cell lines, following treatment with 2 μM of thiostrepton for 24, 48 and 72 hours." (PMID 30728402, 2019). "E2F1 knockdown, therefore, increases apoptosis in colon cancer cells compared with that in normal control cells." (PMID 31534120, 2019). "Studies on colon cancer have demonstrated that the depletion of E2F1 leads to reduced levels of homologous recombination (HR), resulting in interrupted DNA replication and the subsequent accumulation of DNA lesions." (PMID 31534120, 2019). "Expression of E2F1 was not affected by FOXM1 overexpressing HCT116 cells, but in thiostrepton treated HCT116 and HT29 colon cancer cells, E2F1 was downregulated, suggesting that E2F1 is regulated by FOXM1." (PMID 30728402, 2019). "To identify the specific roles of E2F1 in the transcriptional regulation of human colon cancer cells, we examined the expression levels of HR factors following the knockdown of E2F1." (PMID 31534120, 2019). "Recently, our group identified siE2F1 nanoliposomes formulation (called siE2F1-SUV) with a better efficacy of uptake and silencing of E2F1 in cultured human biopsy of colonic mucosa and colon carcinoma cells." (PMID 30050877, 2017). "MiR-34a was previously reported to induce senescence-like growth arrest through modulation of the E2F1/E2F3 expression in human colon cancer cells and leukemic cells." (PMID 28389657, 2017). "The results suggest that high E2F1 expression when combined with high TS expression predicts poor prognosis of patients with colon cancer treated with 5FU-based regimen." (PMID 26831819, 2016). "Our most recent studies show that RING domain of XIAP is crucial for XIAP upregulation of Cyclin D1 expression, while BIR domains specifically mediate E2F1 transactivation and Cyclin E expression in human colon cancer HCT116 cells." (PMID 27447744, 2016). "About 37 and 31 % diference in 3-year DFS and OS respectively were seen between patients with E2F1+TS+ colon cancer immunophenotype as compared to E2F1-TS- immunophenotype." (PMID 26831819, 2016). "About 37 and 31 % difference in 3-year DFS and OS respectively were seen between patients with E2F1+TS+ vs. E2F1-TS- colon cancer immunophenotype." (PMID 26831819, 2016). "Multivariate analysis identified significant association of the combined E2F1+TS+ immunophenotype with worse OS (HR = 3,78, P = 0,009) and DFS (HR = 2,30, P = 0,03) of patients with colon cancer." (PMID 26831819, 2016). "E2F1 overexpressing human fibrosarcoma cells in culture had increased TS levels and were resistant to 5FU, which is consistent with colon cancers exhibiting E2F1+TS+ immunophenotype in our study." (PMID 26831819, 2016). "Kaplan-Meier survival curves confirmed the worst DFS and OS of patients with colon cancer exhibiting E2F1+TS+ immunophenotype." (PMID 26831819, 2016). "Similar effects of E2F1 on TAp73 expression were also observed in RKO colon cancer cells exposed to cisplatin." (PMID 25237903, 2014). "E2F1 expression is elevated in lung metastasis of colon cancer, and correlates with thymidylate synthase expression, resulting in chemoresistance." (PMID 24465681, 2014). "On the other hand, E2F1 is over-expressed in colon tumors with increased apoptosis and low proliferation." (PMID 24465681, 2014). "Furthermore, 5-LO expression was up-regulated upon inhibition of central cell cycle–promoting factors such as CDK4/6 (palbociclib) and E2F1, whereas overexpression of b-Myb attenuated 5-LO levels in the colon cancer cells." (PMID 36849252, 2023). "However, E2F1 has also been described to have both effects: pro‐tumorogenic or antitumor in colon cancer, and these effects on proliferation depended on the type of cancer or cell line." (PMID 37876309, 2023).
colon carcinoma (continued). "Thus, parallel understanding can be drawn in colon carcinoma cells, whereby intact pRb hampers effective functioning of E2F1, preventing E2F1-mediated transcriptional repression of TCF4/β-catenin target genes, leading to an activated Wnt/β-catenin pathway." (PMID 33396222, 2020). "For instance, E2F1 could upregulate the expression of c-Myc and p14ARF, therefore inducing apoptosis in colon cancer cells." (PMID 32117628, 2020). "Importantly, E2F1 has been noted to activate oncogenes to facilitate tumor progression, and its activation on lncRNAs has been documented in colon cancer." (PMID 31934717, 2020). "To determine whether E2F1 localizes to sites of DNA damage, we investigated the colocalization of endogenous E2F1 and γH2AX, which is used to detect DNA DSBs, in human colon cancer cells by immunofluorescence imaging." (PMID 31534120, 2019). "In colon cancer cells, E2F1 and specific HR proteins had accumulated at higher levels (increased by 8.9/5.7-fold for E2F1, 8.7/7.6-fold for RAD51, 11.4/10.8-fold for RAD54, and 5.9/5.1-fold for RPA in HCT116/HT29 cells, respectively) than those in normal colon cells." (PMID 31534120, 2019). "To determine whether E2F1 is involved in DNA replication in colon cancer cells, we conducted the BrdU cell proliferation assay following the transfection of cells with siE2F1." (PMID 31534120, 2019). "E2f1 is a proliferation promoting TF and has been found to be accumulated in colon cancer." (PMID 28588641, 2017). "The significant node of Ezh2 and its TFs such as E2f1, Hsfy2, and Nfyb may show the potential therapeutic effect on colon cancer." (PMID 28588641, 2017). "It seems that the worst survival of patients with colon cancer treated with 5FU-based regimen and exhibiting high TS expression may be attributed to TS expression induced by high level of E2F1 (E2F1+TS+ immunophenotype)." (PMID 26831819, 2016). "Our results also suggest that one way to improve the results of treatment of TS+ colon cancer may be to look for drugs targeting E2F1 or downstream genes of E2F1 other than TS." (PMID 26831819, 2016). "It has to be shown whether colon cancers with E2F1+TS+ immunophenotype, may behave smilarly i.e., may be more sensitive to topo I inhibitors." (PMID 26831819, 2016). "The effects of POH1 on E2F1 expression might also apply to other types of cancer cells such as the colon cancer LoVo cells." (PMID 26510456, 2015). "Interestingly, an inverse relationship between E2F1 and miR-17 has been shown in colon cancer tissue." (PMID 26465597, 2015). "Moreover, a 2.2-fold induction of the PUMA promoter was also noted in the HCT116 PUMA+/+ colon cancer cell line after Ad-E2F-1 infection." (PMID 17263886, 2007). "In addition, we confirmed at the cellular level that aspirin has the ability to inhibit the metastasis of colon cancer cells and demonstrated that aspirin can suppress the expression of metastasis‐related genes (E2F1, VEGFA, MMP3, and CCNE1) in colon cancer cells." (PMID 41425852, 2025). "Importantly, aspirin also inhibited the expression of four highly expressed metastatic genes in colon cancer, including E2F1, CCNE1, VEGFA, and MMP3, which may explain its anti‐tumor and anti‐metastasis effect." (PMID 41425852, 2025). "Furthermore, we have identified significant upregulation of key transcription factor interactions in colon cancer patients, including the apoptotic regulation facilitated by E2F1, MYC, and MYCN, as well as activation of the BCL-2 protein family facilitated by TP73." (PMID 37398471, 2023). "Importantly, the transcriptional of E2F1 on lncRNA has been demonstrated in colon cancer." (PMID 31934717, 2020). "The transcription of the thymidylate synthase gene was regulated by E2F1 in primary colon cancer specimens, the regulatory pattern of which from E2F1 to thymidylate synthase may be highly conserved during malignant progression of colon cancer." (PMID 32117628, 2020).